BDNF (brain derived neurotrophic factor)
Diseases named in the same sentence as BDNF in open-access papers (continued):
Sharing a sentence is not in itself a finding about the gene and the disease.
Cerebral ischemia (continued). "Notably, it has been shown that minocycline upregulates cyclic-AMP response element binding (CREB) and BDNF in the hippocampus of cerebral ischemia rats and improves behavioral deficits, suggesting a shared pathway between minocycline and cAMP signaling." (PMID 38920631, 2024). "However, in our study, Notch pathway was found to be activated after cerebral ischemia, while BDNF was decreased, showing a different trend after ischemic injury." (PMID 39090706, 2024). "Additionally, the inhibition of GSK-3β/CREB/BDNF 98 and MAPK/ERK/CREB/BDNF 73 signaling pathways can upregulate BDNF expression, thereby alleviating cerebral ischemia-reperfusion injury." (PMID 38169754, 2024). "Another example that highlights the connection between BDNF and neurogenesis is the treatment with Panax notoginseng saponins, used in the context of cerebral ischemia injury, that stimulates hippocampal neurogenesis by inducing different pathways, such as the upregulation of BDNF." (PMID 37631295, 2023). "Meanwhile, upregulation of BDNF expression and activation of Akt/mTOR/p70S6K signaling after ME could partially underlie the neuroprotective effects of PNS against cerebral ischemia injury." (PMID 35770087, 2022). "We speculated that BDNF induction may be related to the protective mechanisms of PNS against cerebral ischemia injury." (PMID 35770087, 2022). "Therefore, the BDNF/TrkB signaling and downstream TrkB/Akt signaling protects the injured neurons and promotes the recovery of cerebral ischemia." (PMID 35186478, 2022). "HZP treatment could promote functional recovery by enhancing the expression of brain-derived neurotrophic factor (BDNF) and increasing the level of neurogenesis in cerebral ischemia-reperfusion (I/R) animal." (PMID 36703753, 2022). "We hypothesized that upregulation of brain-derived neurotrophic factor (BDNF) expression and activation of Akt/mTOR/p70S6K signaling after ME could partially underlie the neuroprotective effects of PNS against cerebral ischemia injury." (PMID 35770087, 2022). "Interestingly, our findings differ from a previous animal study that reported an increase in BDNF and TrkB expression in chronic cerebral ischemia in the hippocampus of aged rats." (PMID 35112804, 2022). "Furthermore, NeuN and VEGF expression were higher in the transplanted group and stem cell therapy partially prevented BDNF and neurotrophin-3 over-expression induced by cerebral ischemia." (PMID 35879657, 2022). "Meanwhile, BDNF upregulation and activation of Akt/mTOR/p70S6K pathway could partially underlie the neuroprotective effects of PNS against cerebral ischemia injury." (PMID 35770087, 2022). "Meanwhile, upregulation of brain-derived neurotrophic factor (BDNF) expression and activation of Akt/mTOR/p70S6K signaling after ME could partially underlie the neuroprotective effects of PNS against cerebral ischemia injury." (PMID 35770087, 2022). "In addition, regular consumption of lactobacillus probiotics can also alter the expression of brain-derived neurotrophic factor (BDNF) receptors and increase BDNF concentrations in the brain, which can promote recovery after brain ischemia." (PMID 36401322, 2022). "Taken together, modulations of SDF1-CXCR4 axis and BDNF expression by HBOT as shown in the present study might participate in the repair process after brain ischemia and contribute to motor function improvement." (PMID 35163700, 2022). "Overexpression of BDNF through AAV-BDNF gene therapy promoted the migration of endogenous neuronal progenitor cells from the subventricular zone, which stimulated animals’ functional recovery after brain ischemia modeling." (PMID 36077134, 2022). "It increased the levels of acetylated histone H3, neural cell adhesion molecule nestin, glial fibrillary acidic protein, transcription factor CREB (phospho-cAMP response element-binding protein), and brain-derived neurotrophic factor (BDNF) that were reduced after cerebral ischemia." (PMID 34680562, 2021).
Cerebral ischemia (continued). "Atorvastatin used in the treatment of cerebral ischemia in animals led to recovered BDNF levels." (PMID 34064670, 2021). "However, the precise protective mechanisms of BCL during cerebral ischemia/reperfusion through BDNF-TrkB remain to be studied." (PMID 34234667, 2021). "Cerebral ischemia suppressed GAD1 expression by decreasing hippocampal BDNF expression." (PMID 33920851, 2021). "Moreover, LN-binding BDNF constructed via fusing with laminin-binding domain (LBD) to BDNF (LBD-BDNF) was widely applied for the treatment of cerebral ischemia and reperfusion injury, facial nerve injury, and recurrent laryngeal nerve injury 33, 84-86." (PMID 32724468, 2020). "The mechanisms underlying this phenomenon are not fully understood, but they may result from the modulatory multidirectional role of BDNF in neurogenesis, pain pathophysiology, and synapsis functioning that was previously reported in brain ischemia." (PMID 33020432, 2020). "A direct application of BDNF is neuroprotective in focal and global cerebral ischemia models." (PMID 30217051, 2018). "Cerebral ischemia in rats led to the upregulation of the BDNF precursor protein (proBDNF), mature BDNF (mBDNF), and their processing enzymes, such as furin and prohormone convertases, in the intracellular milieu, and matrix metalloproteinases (MMPs) or plasmin in the extracellular milieu." (PMID 29997355, 2018). "A recent study found that genes and proteins of brain-derived neurotrophic factor (BDNF), proBDNF and their processing enzymes such as tissue plasminogen activator (tPA), furin, and matrix metalloproteinases (MMPs) lead to up-regulation in cerebral ischemia." (PMID 29997355, 2018). "In addition, the results indicated that DCH treatment for 28 days improved cognitive function by promoting neurogenesis and expression of BDNF protein in DG after cerebral ischemia and reperfusion." (PMID 28769792, 2017). "On the other hand, recent studies reported that brain-derived neurotrophic factor (BDNF), a representative neurotrophic factor in the brain, played a neuroprotective role following cerebral ischemia injuries, and evidence is accumulating to show that BDNF is important for ischemic brain therapy." (PMID 25850013, 2015). "Furthermore, the mechanism for the Gadd45b effect on BDNF under brain ischemia is still poorly understood." (PMID 26698301, 2015). "NPAS4 is gradually normalized via its own feedback loop, which may explain why BDNF mRNA expression is transiently increased following cerebral ischemia." (PMID 24669275, 2014). "Intracranial infusion of BDNF significantly reduces infarct volume after induction of cerebral ischemia, and intravenous infusion of BDNF enhances functional recovery and endogenous neurogenesis, suggesting that BDNF may protect cells from ischemic injury." (PMID 24672780, 2014). "Overexpression of brain-derived neurotrophic factor (BDNF) during cerebral ischemia induces expression of miR-132, which in turn increases the expression of NMDA receptor (NR2A and NR2B subunits) and mGluR (glutamate receptor, ionotropic, AMPA1 (alpha 1), GluR1)." (PMID 24961318, 2013). "BDNF is a potent growth factor involved in recovery following cerebral ischemia." (PMID 23356671, 2013). "A blockade of endogenous BDNF activity exacerbates the effects of cerebral ischemia." (PMID 23912236, 2013). "A preclinical study demonstrated that post-insult treatment with sodium butyrate stimulated cell proliferation, migration and differentiation through the upregulation of the brain-derived neurotrophic factor (BDNF) in the ischemic brain of rats subjected to permanent cerebral ischemia." (PMID 22414433, 2012). "Studies in rats have shown that cerebral ischemia can differently affect BDNF levels in the core, where a decrease occurs, and penumbra areas where an increase occurs, supporting a role for protection by BDNF." (PMID 21949858, 2011).
Cerebral ischemia (continued). "Indeed studies in both mice and rats have demonstrated that administration of exogenous BDNF can promote a reduction in infarct volume and functional recovery after cerebral ischemia." (PMID 21949858, 2011). "In response to cerebral ischemia the production of several neurotrophic factors, including fibroblast growth factor 2, insulin-like growth factor 1 and brain-derived neurotrophic factor (BDNF) is increased." (PMID 21949858, 2011). "This study is intended to compare the effectiveness between voluntary, involuntary, and forced exercises under similar training intensity with the evaluation of the motor recovery, and their functions of regulating corticosterone and brain BDNF levels after brain ischemia in a rat model." (PMID 21347437, 2011). "In adult rodents, BDNF also showed characteristics of neuroprotection which promoted survival of hippocampal, striatal, and septal neurons in culture and in vivo by protecting the brain against such insults as focal brain ischemia." (PMID 21347437, 2011). "Thus, an increased BDNF expression upon IH exposure may be a protective response of non-neuronal cells to IH-induced brain damage, similar to the increase in BDNF levels during cerebral ischemia." (PMID 40490588, 2025). "DMF is capable of providing neurotrophic factors, such as BDNF, GDNF, and NT3, these neurotrophic molecules being directly related to axonal elongation after peripheral nerve injury and during development and also having been associated with motor recovery after cerebral ischemia." (PMID 37571065, 2023). "After cerebral ischemia, the increased expression of brain-derived neurotrophic factor (BDNF), platelet-derived growth factor-B (PDGF-B), transforming growth factor-beta (TGF-β), fibroblast growth factor 2 (FGF2), and VEGF, may promote both angiogenesis and axonal outgrowth." (PMID 35873557, 2022). "As such, BDNF may have therapeutic potential for the treatment of neurological disorders, such as cerebral ischemia‐reperfusion injury, neuroinflammation‐related brain injury, age‐related memory impairment, Parkinson’s disease, Alzheimer’s disease, and postoperative cognitive dysfunction." (PMID 35112804, 2022). "Notably, taVNS has been shown to induce neuroprotection against cerebral ischemia/reperfusion injury, which might be related to the upregulation of BDNF expression in the ischemic cortex." (PMID 34526917, 2021). "Besides the injection of exogenous BDNF, there are relevant data that Galectin-1 (Gal-1), a soluble carbohydrate-binding protein that is widely expressed in both neurons and glia, can enhance astrocytic BDNF production and improve functional outcomes in rats following brain ischemia." (PMID 34113618, 2021). "Likewise, it was shown that Hpc-bone marrow MSCs (BM-MSCs) enhanced the angiogenesis and neurogenesis in cerebral ischemia rat model through upregulation of growth factors including BDNF, GDNF, VEGF, and erythropoietin with downregulation of inflammatory cytokines." (PMID 33381188, 2020). "The up-regulated BDNF may inhibit cell apoptosis in the cerebral ischemia rat." (PMID 30029590, 2018). "Notably, EA at the Baihui acupoint may facilitate the recovery of motor function and stimulate brain-derived neurotrophic factor (BDNF) and receptor tyrosine kinase B expression in rats with cerebral ischemia." (PMID 28913350, 2017). "Similarly, BDNF plays a central role in neuronal recovery after cerebral ischemia." (PMID 28865453, 2017). "Interestingly, endurance training stimulated endogenous BDNF/tkrB expression and may play a neuroplastic role following cerebral ischemia or intracerebral hemorrhage in rat and mice." (PMID 26682073, 2015). "And Gadd45b maybe affect the level of BDNF by demethylation of CpG islands in brain ischemia." (PMID 26698301, 2015).
Cerebral ischemia (continued). "Therefore, we can hypothesize that under cerebral ischemia, the BDNF promoter IV may be damaged, not only affecting the normal process of synaptic pruning but also potentially causing a reduction in GABAergic synapses, further exacerbating the neuronal damage caused by cerebral ischemia." (PMID 40313098, 2026). "MSCs enhance brain plasticity after cerebral ischemia by releasing nutrients and growth factors such as VEGF, BDNF, and bFGF, while also promoting neural repair by inhibiting the expression of pro-inflammatory factors." (PMID 40949877, 2025). "BDNF is an endogenous factor involved in neurogenesis in the central nervous system (CNS), especially in the hippocampal region, and an increase in its level after cerebral ischemia may indicate that the nerve cells are in a more favorable environment for recovery." (PMID 39749196, 2024). "Neurotrophins such as BDNF, NGF and NT-4 have been demonstrated to promote neurogenesis after cerebral ischemia." (PMID 38234630, 2024). "Brain-derived neurotrophic factor (BDNF) and nerve growth factor (NGF) are members of the neurotrophic factor family, which are important regulators of neuroregeneration after cerebral ischemia." (PMID 39090706, 2024). "And M2 macrophages enhance neurogenesis and angiogenesis by secreting various neurotrophic factors such as IGF-1, BDNF and VEGF, and promote the recovery of neurological function after cerebral ischemia/reperfusion injury in rats." (PMID 37032832, 2023). "In additional animal models of brain ischemia, CBD increased hippocampal BDNF protein levels, stimulated neurogenesis and promoted dendritic restructuring." (PMID 37144214, 2023). "Using OGD as in vitro model for brain ischemia, we demonstrate that after OGD, there is increased BDNF mRNA." (PMID 35307349, 2022). "Neuronal AhR activation after cerebral ischemia inhibits CREB signaling and pro-survival pathways subsequently activated by CREB, such as increased expression of brain-derived neurotrophic factor and bcl-x." (PMID 33804845, 2021). "Our data are intriguing in that some subjects without known cerebral arteriopathy have elevations of neuroprotective proteins, BDNF and NRG-1, suggesting a response to subclinical cerebral ischemia in children with SCA." (PMID 35935682, 2021). "Many neurotrophic factors, including BDNF, NGF, and NT-4 have been demonstrated to protect neural stem cells (NSCs) and to promote neurogenesis after cerebral ischemia." (PMID 34025400, 2021). "Then we used OGD to induce cerebral ischemia–reperfusion injury (IRI) in vitro and found that BDNF expression was decreased and apoptosis was increased after OGD treatment." (PMID 33413076, 2021). "The results showed that cerebral ischemia considerably inhibited the expression of SNHG16 and BDNF but promoted the expression of miR-10b-5p compared with the control group in the rat model." (PMID 32323054, 2020). "In the CNS, they are involved in neuroprotection against brain ischemia by increasing NGF and BDNF, important factors involved in the recovery of brain activities after an ischemic insult." (PMID 32344922, 2020). "Further, its overexpression was found to promote angiogenesis and neurogenesis and improve the prognosis of mice with cerebral ischemia by upregulating vascular endothelial growth factor (VEGF) and brain-derived neurotrophic factor (BDNF) levels." (PMID 31164807, 2019). "In the present study, with regard to BDNF and GDNF, cerebral ischemia increased its protein expression levels, which is consistent with a previous study that reported elevated BDNF and GDNF protein expression in transient cerebral ischemia." (PMID 30046341, 2018). "It has been also demonstrated that cerebral ischemia increases the cortical expression of VEGF, BDNF, SDF-1α and Ang1, molecules that induce changes in the vasculature and induce the glial tube to help the migration of neuroblasts to the ischemic lesion." (PMID 29180821, 2017).
Cerebral ischemia (continued). "In our preclinical findings, protein analysis showed that both BDNF and GFAP levels were downregulated by cerebral ischemia while a local and sustained increase in their expression in the perilesioned tissue followed oral administration of co-ultraPEALut." (PMID 26706245, 2016). "Experimental and clinical studies have shown that BDNF and GDNF are upregulated at very early stages during brain ischemia." (PMID 26706245, 2016). "There have been a number of attempts to develop neuroprotectants for brain ischemia, such as FGF-2, a brain-derived neurotrophic factor that has been tested for its ability to rescue neurons from ischemic cell death." (PMID 25237906, 2014). "Under experimental cerebral ischemia and exercise conditions, the expression profiles of NT4/trkB as well as NGF/trkA and BDNF/trkB are changed." (PMID 23526925, 2013). "Pretreatment with EA increased the production of BDNF and SDF-1α, which elicited protective effects against focal cerebral ischemia." (PMID 23356671, 2013). "Previous reports demonstrated that transplantation of gene-modified human MSCs overepressing GDNF, BDNF, or VEGF after cerebral ischemia reduce infarct volume and ameliorate neurological deficits." (PMID 20668522, 2010). "However, numerous studies report that reactive astrocytes produce various neurotrophins, including BDNF, GDNF, and CNTF, to protect neurons after cerebral ischemia." (PMID 37704780, 2024). "In a study of middle-aged female rats, treated with WBV from 1 to 30 days after mid-cerebral ischemia-reperfusion, decreased inflammasome activation (caspase-1 and IL1-beta) and increased brain-derived neurotrophic factor (BDNF) expression were observed, concomitant with infarct reduction." (PMID 36960421, 2023). "Rutin boosts the levels of estrogen receptor alpha and beta (ERα and ERβ), which modulate the growth, survival and metabolism of cells by regulating downstream targets and activating the BDNF-TrkB and NGF-TrkA signaling pathways, to mitigate cerebral ischemia injury." (PMID 35833035, 2022). "HDAC6 is upregulated in a Rett syndrome model, has a negative effect on BDNF trafficking, and is involved in T-cell regulation in neuroinflammation after brain ischemia." (PMID 34638996, 2021). "Optimized integration of TP and Ki20227 can improve cerebral ischemia by inhibiting CSF1R signal and trigger autophagy and BDNF-Akt signaling pathways to increase dendritic spine density and synaptic protein expressions, which in turn enhances neurobehavioral function." (PMID 33192177, 2020). "The increased expression of brain-derived neurotrophic factor (BDNF) may be relevant to the recovery of neural function and plasticity after cerebral ischemia." (PMID 32670064, 2020). "Another study in experimental cerebral ischemia has also found that neurons but not astrocytes expressed BDNF mRNA in the ischemic striatum." (PMID 31307481, 2019). "Some experiments found that exogenous T3 and T4 elevated the concentrations of certain important neuroprotective agents, such as brain-derived neurotrophic factor (BDNF) and glial cell-derived neurotrophic factor (GDNF), in a rat model of brain ischemia/reperfusion." (PMID 29176727, 2017). "In this study, T3 was intra-ventricularly injected to evaluate gene expression and protein concentration of and brain-derived neurotrophic factor (BDNF) and Glial cell-derived neurotrophic factor (GDNF) in hippocampal CA1 region in rat model of brain ischemia/reperfusion (I/R)." (PMID 28202057, 2017). "Enhanced expression of BDNF, EGF, EPO, and bNGF after cerebral ischemia or traumatic brain injuries may contribute to the activation of neurogenesis in the SVZ." (PMID 27832087, 2016). "Transplanted human BM-MSCs in the brains of cerebral ischemia rats induced behavioral recovery by elevating BDNF, NT-3 and VEGF levels, but our results showed that ASCs didn’t significantly affect the level of BDNF." (PMID 23049854, 2012).